SH2B1 (SH2B adaptor protein 1)
Description:
Adapter protein for several members of the tyrosine kinase receptor family. Involved in multiple signaling pathways mediated by Janus kinase (JAK) and receptor tyrosine kinases, including the receptors of insulin (INS), insulin-like growth factor 1 (IGF1), nerve growth factor (NGF), brain-derived neurotrophic factor (BDNF), glial cell line-derived neurotrophic factor (GDNF), platelet-derived growth factor (PDGF) and fibroblast growth factors (FGFs). In growth hormone (GH) signaling, autophosphorylated ('Tyr-813') JAK2 recruits SH2B1, which in turn is phosphorylated by JAK2 on tyrosine residues. These phosphotyrosines form potential binding sites for other signaling proteins. GH also promotes serine/threonine phosphorylation of SH2B1 and these phosphorylated residues may serve to recruit other proteins to the GHR-JAK2-SH2B1 complexes, such as RAC1. In leptin (LEP) signaling, binds to and potentiates the activation of JAK2 by globally enhancing downstream pathways. In response to leptin, binds simultaneously to both, JAK2 and IRS1 or IRS2, thus mediating formation of a complex of JAK2, SH2B1 and IRS1 or IRS2. Mediates tyrosine phosphorylation of IRS1 and IRS2, resulting in activation of the PI 3-kinase pathway. Acts as a positive regulator of NGF-mediated activation of the Akt/Forkhead pathway; prolongs NGF-induced phosphorylation of AKT1 on 'Ser-473' and AKT1 enzymatic activity. Enhances the kinase activity of the cytokine receptor-associated tyrosine kinase JAK2 and of other receptor tyrosine kinases, such as FGFR3 and NTRK1. For JAK2, the mechanism seems to involve dimerization of both, SH2B1 and JAK2. Enhances RET phosphorylation and kinase activity. Isoforms seem to be differentially involved in IGF1 and PDGF-induced mitogenesis (By similarity).
Synonyms: PSM; SH2B; FLJ30542
Tractability: Small molecule: a structure with a bound ligand is known. Antibody: its Gene Ontology location is reachable by antibodies, with medium confidence. PROTAC: ubiquitination databases record sites on it; its protein half-life has been measured.
Gene: Protein-coding gene on chromosome 16 (28,846,600 to 28,874,212, forward strand). Ensembl gene ENSG00000178188.
Subcellular location: Cytoplasm; Membrane; Nucleus
Subcellular location (Human Protein Atlas): Nucleoplasm; Centriolar satellite; Cytosol
Pathways (Reactome):
Immune System: Growth hormone receptor signaling; Prolactin receptor signaling
Hemostasis: Factors involved in megakaryocyte development and platelet production
Signal Transduction: Signaling by Leptin
Gene Ontology:
Molecular function: protein binding; transmembrane receptor protein tyrosine kinase adaptor activity; signaling adaptor activity
Biological process: positive regulation of SMAD protein signal transduction; intracellular signal transduction; cell surface receptor protein tyrosine kinase signaling pathway; signal transduction
Cellular component: cytosol; plasma membrane; cytoplasm; membrane; nucleus
Genetic constraint (gnomAD): Loss-of-function variants: 14 observed, 58.56 expected, observed/expected ratio (o/e) 0.24, 90% interval 0.16 to 0.37. The upper end of that interval is the gene's LOEUF score, 0.37, which puts it in group 1 of 6, group 1 being the genes least tolerant of losing a copy. Missense variants: 914 observed, 982.83 expected, observed/expected ratio (o/e) 0.93, 90% interval 0.88 to 0.98. Synonymous variants: 433 observed, 426.39 expected, observed/expected ratio (o/e) 1.02, 90% interval 0.94 to 1.1.
Homologues: Orthologues: chimpanzee SH2B1 (99% identical), pig SH2B1 (94% identical), guinea pig SH2B1 (92% identical), mouse Sh2b1 (92% identical), dog SH2B1 (83% identical), rat Sh2b1 (80% identical), zebrafish sh2b1 (43% identical), Drosophila melanogaster Lnk (26% identical). Paralogues in human: SH2B2 (36% identical), SH2B3 (28% identical).
Diseases named in the same sentence as SH2B1 in open-access papers:
SH2B1 is named in the same sentence as 67 diseases in open-access papers, as found by Europe PMC text mining. Sharing a sentence is not in itself a finding about the gene and the disease. The quoted sentences say what the papers report.
Obesity (111 papers, 2009 to 2026). Accumulation of substantial excess body fat. "The SH2B1 gene, recently identified as a candidate for non-syndromic monogenic obesity, encodes an intracellular adaptor protein involved in signaling pathways downstream of receptor tyrosine kinases, including leptin, BDNF, and insulin receptors." (PMID 40077044, 2025). "Rare deleterious mutations in SH2B1 can lead to non-syndromic monogenic obesity, characterized by hyperphagia and severe early-onset obesity." (PMID 40077044, 2025). "Specific genotype combinations of MC4R rs17782313 and SH2B1 rs7359397 (TC-CC and TC-CT) confer a substantially elevated obesity risk−15.58-fold higher than other genotypes—through synergistic regulation of the leptin–melanocortin pathway." (PMID 41340654, 2025). "Loss-of-function SH2B1 mutations have been strongly linked to obesity based on data from genomic structural variation studies, GWAS, and animal models." (PMID 40077044, 2025). "Individuals with variants in SH2B1 exhibit a wide range of phenotypes including obesity, insulin resistance, and neurodevelopmental problems, while variants in other related obesity genes result in a diverse phenotypic spectrum which includes obesity." (PMID 38297031, 2024). "This locus includes the SH2B adaptor protein 1 (SH2B1) gene, linked to the development of obesity phenotype." (PMID 39897959, 2024). "SH2B1 mutations are associated with obesity, type 2 diabetes, and metabolic dysfunction‐associated steatotic liver disease (MASLD) in humans." (PMID 38885417, 2024). "Here, we further investigated SH2B1 as a genetic locus underlying the association between obesity and FI." (PMID 38434247, 2023). "Recent studies have shown that SH2B1, a gene implicated in leptin and insulin signaling, is a substantial contributor to the genetic architecture of obesity." (PMID 38434247, 2023). "SH2B1 has been identified as a susceptibility locus for obesity in several BMI- or obesity-related GWASs in different human cohorts." (PMID 38434247, 2023). "Supporting this, Sh2b1-deficient animals develop obesity and metabolic syndrome, while humans with SH2B1 loss-of-function mutations present with hyperphagia, childhood-onset obesity, disproportionate insulin resistance, and reduced adult height." (PMID 38434247, 2023). "In humans, rare heterozygous loss-of-function mutations in SH2B1 have been identified in children with hyperphagia, severe obesity, hyperinsulinemia, and maladaptive behavior." (PMID 37586323, 2023). "In human genome-wide association studies, numerous SH2B1 single-nucleotide polymorphisms (SNPs) have been identified to link to obesity, type 2 diabetes, and cardiovascular diseases." (PMID 32251290, 2020). "Being pathogenic for both obesity and insulin resistance, SH2B1 is a strong candidate for involvement in NAFLD risk and severity." (PMID 32365683, 2020). "Deletion of chromosomal 16p11.2, which encompasses the SH2B1 gene, is associated with severe obesity in humans." (PMID 32251290, 2020). "Previous studies have demonstrated that natural loss-of-function mutations in the SH2B1 gene in humans lead to both elevated food intake and severe obesity associated with leptin resistance." (PMID 31341224, 2019). "Deletions of the 16p11.2 harboring SH2B1 were pathogenic and were linked to developmental delay in addition to obesity." (PMID 31379474, 2019). "The Chr16p11 gene set consists of 212 genes, some of which are associated with obesity, including SH2B1, APOBR, SULT1A1, SULT1A2, and TUFM." (PMID 29854750, 2018). "SH2B1 is an activator of leptin signaling, and deletions or mutations in the SH2B1 gene are associated with severe obesity in humans and mice." (PMID 28912580, 2017). "Previous studies on the causal variation underlying the obesity association of chr16p11.2 mainly focused on the SH2B1 gene." (PMID 25955518, 2015).
Obesity (continued). "In SH2B1 we detected a rare mutation solely in obese individuals; additionally we replicated the obesity association of the GWAS SNP rs7498665 (SH2B1: p.Thr484Ala;)." (PMID 25955518, 2015). "The coding variant rs7498665 (SH2B1: p.Thr484Ala) was identified in GWAS studies as lead obesity association signal for a linkage disequilibrium block encompassing 1 Mb." (PMID 25955518, 2015). "The relevance of SH2B1 locus in human energy balance is strengthened by the identification via GWAS of common variants near SH2B1 associated with BMI variation or obesity risk." (PMID 25825681, 2015). "Variants in APOBR contributed as strongly as variants in SH2B1 to the association with extreme obesity in the chromosomal region chr16p11.2." (PMID 25955518, 2015). "Here, we identify 4 additional SH2B1 variants by sequencing 500 individuals with severe early-onset obesity." (PMID 24971614, 2014). "In summary, we have identified additional SH2B1 variants in individuals with obesity and that implicate SH2B1 isoforms besides SH2B1β as important for the regulation of body weight." (PMID 24971614, 2014). "Here, we describe the identification of 4 novel variants in SH2B1 that are present in individuals with obesity and insulin resistance." (PMID 24971614, 2014). "Our results showed that SH2B1 rs7498665 was significantly associated with the risk of overweight/obesity among 6,142 cases and 4,345 controls from four studies (overall OR = 1.21, 95% CI = 1.09-1.34, P = 0.0004)." (PMID 24621099, 2014). "Our results showed that SH2B1 rs7498665 polymorphism was significantly associated with the risk of overweight/obesity (overall odds ratio (OR) = 1.21, 95% confidence interval (CI) = 1.09-1.34, P = 0.0004)." (PMID 24621099, 2014). "Our results confirmed the relationship between SH2B1 and the risk of overweight/obesity (overall OR = 1.21, 95% CI = 1.09-1.34, P = 0.0004)." (PMID 24621099, 2014). "Here, we describe 4 additional SH2B1 variants identified by sequencing a further 500 unrelated severely obese individuals from the Genetics of Obesity Study (GOOS) cohort." (PMID 24971614, 2014). "We previously identified 4 variants in SH2B1 (P90H, T175N, P322S, and F344Lfs*20) in individuals with severe early-onset obesity from the GOOS cohort." (PMID 24971614, 2014). "There is evidence to support not only the role of rare variants in SH2B1 in severe obesity but also of common variants with a broader role in the regulation of body mass index (BMI)." (PMID 24971614, 2014). "Many SH2B1 SNPs and missense SH2B1 mutations have been reported to be linked to obesity and type 2 diabetes in humans." (PMID 24358267, 2013). "The reported disproportionate hyperinsulinaemia in carriers of these deletions is reminiscent of the phenotype of SH2B1 knockout mice, which previously led to the suggestion that haploinsufficiency of SH2B1 is the primary cause of obesity in these individuals." (PMID 23554873, 2013). "Human subjects with SH2B1 mutations have also been reported to result in hyperphagia, obesity, insulin resistance, reduced height and behavioral abnormalities." (PMID 24260264, 2013). "SNPs in human SH2B adapter protein 1 gene (SH2B1) are also been shown to be associated with leptin resistance and obesity." (PMID 23825611, 2013). "Variations close to or in the SH2B1 gene have been found to be associated with obesity in two large genome-wide association studies." (PMID 22474595, 2012). "A deletion of ~200 kb covering SH2B1 was recently shown to be associated with severe early-onset obesity, whereas the corresponding reciprocal duplication was associated with leanness." (PMID 23270367, 2012). "Association with obesity was also shown for a coding SNP in SH2B1 (rs7498665: g.8164A/G, Thr484Ala;)." (PMID 23270367, 2012). "SH2B1 has been implicated in neuronal differentiation, cell growth, metabolism, obesity and diabetes." (PMID 20868529, 2010).
Obesity (continued). "Furthermore, SH2B1—which regulates energy balance through insulin sensitivity and adipocyte function—shows male-specific obesity association at the rs7359397 locus." (PMID 41340654, 2025). "Deletion of Sh2b1 in DRN‐projecting PVHSH2B1 neurons causes obesity, insulin resistance, and MASLD." (PMID 38885417, 2024). "SH2B1 has been associated with the obesity phenotype and ATXNL2 could play a role in central nervous system malfunction." (PMID 39202413, 2024). "SH2B1 deficiency induces obesity and metabolic disease in mice and humans." (PMID 38885417, 2024). "In addition, pathogenic variants in SH2B1 in young adults with severe obesity corroborate the role of this adaptor protein." (PMID 36674935, 2023). "SH2B1 is the most likely obesity-causing gene in this region." (PMID 37142702, 2023). "However, 6 BMI index SNPs had positive genetic estimates for both PCOS and pre-eclampsia, including rs1121980 in the adipose-associated gene FTO and rs7498665 in SH2B1, linked to insulin resistance in obesity." (PMID 35104295, 2022). "A GWAS study in Danish, Icelandic, Dutch, European Americans, and African American adults has shown that SNPs in the FTO, MC4R, BDNF, and SH2B1 genes are highly associated with obesity risk via modulating leptin secretion to induce leptin resistance in different ethnicities." (PMID 34836030, 2021). "Human SH2B1 missense mutations are cosegregated with the obesity and metabolic disease traits." (PMID 32251290, 2020). "However, among the SH2B1 genetic variants identified as related to obesity traits, the polymorphism rs7359397 has been associated with glycosylated hemoglobin and insulin sensitivity." (PMID 32365683, 2020). "SH2B1 was one of the genes in this gene set, which was demonstrated to be associated with obesity." (PMID 29854750, 2018). "In humans, loss of function mutations in SH2B1 patients resulted in severe early onset obesity." (PMID 25825681, 2015). "It is interesting to note that while deletion of a region on chromosome 16 that contains SH2B1 increases the risk of obesity significantly, reciprocal duplication of this region results in an increase in gene dosage which influences BMI in the reverse manner (leanness)." (PMID 25825681, 2015). "Interestingly, SH2B1 is known to be involved in leptin and insulin signaling and has been reported as a predisposing factor for obesity." (PMID 26293599, 2015). "SH2B1 has been identified to be related to obesity through genome-wide association studies (GWAS)." (PMID 24621099, 2014). "We previously showed that individuals carrying heterozygous variants in the 1–631 region of SH2B1 were hyperphagic, with a reduced final height, elevated plasma insulin levels that are disproportionate to the degree of obesity, and surprisingly, maladaptive behavior." (PMID 24971614, 2014). "A663V variants did not cosegregate with obesity in families in a classical Mendelian manner, suggesting that SH2B1 variants may predispose to obesity against a background of other genetic and environmental factors." (PMID 24971614, 2014). "Impaired SH2B1 function is associated with obesity and type 2 diabetes in humans." (PMID 24358267, 2013). "Additionally, a larger interspersed deletion extending through a 593 kb region on chromosome 16p11.2-p12.2 covering SH2B1 has been associated with developmental delay, feeding difficulties, dysmorphic facial features, and obesity." (PMID 23270367, 2012). "SH2B1 deletions are associated with severe early-onset obesity." (PMID 22474595, 2012). "This deletion encompasses the SH2B1 gene which is implicated in murine obesity." (PMID 22043167, 2011). "In addition, the SH2B1 locus was recently associated with common obesity by genome-wide association studies (GWAS)." (PMID 22043164, 2011).
Obesity (continued). "The SH2B1 gene is for instance an interesting candidate as SNPs at the SH2B1 locus are associated with BMI by GWAS, rare deletions including SH2B1 are associated with a Mendelian form of obesity and inactivation of SH2B1 in mice leads to hyperphagia, leptin resistance and obesity." (PMID 22043165, 2011). "SH2B1 is a strong prior candidate for regulating body weight; it is implicated in leptin signaling; Sh2b1-null mice are obese; and the evidence suggests that the effects of this gene on obesity are mediated through the central nervous system (see Leptin, hypothalamus and AIS)." (PMID 19878575, 2009). "One case has 16p11.2 (distal, BP2-BP3), SH2B1, a critical gene which has been reported in association with a variable and incompletely penetrant phenotype that may include developmental delay, obesity, behavioral problems, schizophrenia, and craniofacial dysmorphism." (PMID 34285689, 2021). "However, the absence of evidence in our data to support this phenotype reopens the possibility that haploinsufficiency of one of the other genes in the region is responsible for the observed GSV-associated obesity phenotype (although SH2B1 remains a strong candidate)." (PMID 23554873, 2013). "In addition, based on the evidence for involvement of SH2B1 in energy homeostasis, rare coding variants in the gene could potentially result in monogenic obesity." (PMID 23270367, 2012). "Mutations associated with monogenic obesity follow autosomal recessive (LEP, LEPR, POMC, and PCSK1) or autosomal dominant (MC4R, SH2B1, SIM1, GNAS) modes of inheritance." (PMID 41751424, 2026). "Research results indicate that the deletion or dysfunction of Sh2b1 leads to cold intolerance, obesity, insulin resistance, and hepatic steatosis, whereas overexpressing Sh2b1 has a protective effect." (PMID 40452923, 2025). "In mice, genetic disruption of Sh2b1 also results in obesity, insulin resistance, type-2 diabetes, severe leptin resistance, and metabolic dysfunction-associated steatotic liver disease." (PMID 39948378, 2025). "By affecting this axis, Sh2b1 plays a significant role in body temperature regulation and energy metabolism, as well as obesity and metabolic diseases." (PMID 40452923, 2025). "Seven publications reported outcomes of MBS in patients with obesity caused by rare variants in LEPR, MC4R, NCOA1, PCSK1, POMC, SH2B1, or SIM1." (PMID 40560452, 2025). "Ablation of SH2B1 resulted in energy imbalance, obesity, and metabolic dysfunction via repressing BDNF action in mice." (PMID 41410190, 2025). "A previous study reported that SH2B1 knockout led to metabolic disorders, such as hyperglycemia, hyperlipidemia, and obesity in mice, suggesting the crucial role of SH2B1 in the maintenance of glucose homeostasis." (PMID 41410190, 2025). "The critical roles of these pathways in regulating food intake, energy expenditure, and glucose homeostasis underscore the importance of SH2B1 in obesity development and insulin resistance." (PMID 40077044, 2025). "Monogenic obesity, often characterized by early-onset and severe obesity, results from rare mutations in genes such as LEP (leptin), MC4R (melanocortin 4 receptor), and SH2B1 (SH2B adaptor protein 1)." (PMID 40004938, 2025). "In our research, 11.86% of the subjects presented with genetic alterations in obesity-associated genes, with 16% of these modifications involving concurrent duplications in SEZ6L2-1 and SH2B1-2, linked to doubled insulin and tripled HOMA-IR levels." (PMID 40429924, 2025). "Given that LepRb‐expressing neurons are sparse in the PVH, it is unlikely that SH2B1 in the PVH protects against obesity by directly enhancing leptin signaling." (PMID 38885417, 2024). "Several of the high-scoring genes (score ≥ 11) are known to be implicated in obesity (such as DGKI [score: 22.8], MC4R [19.6], BDNF [19.6], MTOR [16.8], SH2B1 [14.8], GIPR [14.3], AKT3 [11.6], and LEPR [11.6])." (PMID 38754426, 2024).